FANCA (FA complementation group A)
Diseases named in the same sentence as FANCA in open-access papers (continued):
Sharing a sentence is not in itself a finding about the gene and the disease.
gastric cancer (4 papers, 2023 to 2024). A primary or metastatic malignant neoplasm involving the stomach. "The molecular mechanisms of gastric cancer development in FANCA and FANCD2 mutations are complex and require further research to fully understand." (PMID 37623222, 2023). "Mutations in the FANCA and FANCD2 genes can increase the risk of gastric cancer by disrupting the DNA damage response pathway." (PMID 37623222, 2023). "Furthermore, the mRNA expression of FANCA in gastric cancer patients was categorized into high and low-expression groups based on the median value." (PMID 38682160, 2024). "For c.1320+1G>A in the CDH1 gene and c.G1874C in the FANCA gene we used DNA samples isolated from the peripheral blood of 200 patients with gastric cancer and 200 healthy donors, as well as 70 DNA samples from the tumor tissue of the stomach of patients with cancer." (PMID 36833207, 2023).
glioma (4 papers, 2019 to 2026). A benign or malignant brain and spinal cord tumor that arises from glial cells (astrocytes, oligodendrocytes, ependymal cells). "Blood–brain barrier penetrant PARP inhibitors may be effective in glioma patients carrying GVs in ATM, BRCA2, BRIP1, FANCA, and SDHA identified here that are associated with HRR deficiency, and may act synergistically with radio-, chemo-, and immunotherapy." (PMID 41546701, 2026). "Gliomas from SDHA GV carriers with less DSB accumulation showed a trend towards a higher mean nuclear IRS of RAD51 than those from ATM, BRCA2, and FANCA GV carriers with more DSBs." (PMID 41546701, 2026). "Among the most strongly decreased candidates, we observed proteins related to DNA repair (FANCA, USP38, NET1), autophagy (BCAS3), cancer cell migration and/or invasion (RASSF2, KMO, BCAS3), as well as proteins that can be generally considered as pro-tumorigenic, particularly in glioma (KMO, BCAS3)." (PMID 39833546, 2025). "The mean nuclear IRS of phospho-H2AX indicating DSB accumulation was lowest in gliomas from SDHA versus ATM, BRCA2, and FANCA GV carriers, although the differences were not statistically significant, possibly because SDHA variants are least directly linked to impaired DSB repair." (PMID 41546701, 2026).
hereditary cancer (4 papers, 2020 to 2025). Malignant neoplasms occurring in families at a rate greater than that expected by chance and caused by germline mutations in a specific gene. "A prospective cohort of 1021 unrelated cancer cases with clinical suspicion of hereditary cancer was screened for mutations in the following 14 FA genes: FANCA, FANCB, FANCC, FANCD2, FANCE, FANCF, FANCG/XRCC9, FANCI, FANCL/PHF9, FANCM, FANCP/SLX4, FANCQ/ERCC4, FANCR/RAD51 and FANCU/XRCC2." (PMID 32235514, 2020). "In addition to mutations associated with risk of hereditary cancer, pathogenic/likely pathogenic mutations were detected in ERCC2 (n = 1), FANCA (n = 1), FANCC (n = 1), HNF1A (n = 1), PRF1 (n = 1) RECQL4 (n = 2), WRN (n = 1), and XPA (n = 1)." (PMID 31963545, 2020). "However, this association must be taken with caution since 3% of our in-house control cohort (from GCAT, Genomes for Life Cohort) carried deleterious FANCA mutations compared with 0.6% of the European non-Finnish cohort, being 0.98% in our complete cohort of hereditary cancer patients." (PMID 32235514, 2020).
Premature ovarian insufficiency (4 papers, 2019 to 2022). Amenorrhea due to loss of ovarian function before the age of 40. "With the analysis of target genes, we found that the FANCA gene is associated with the processes of DNA damage repair and the variation of FANCA would induce premature ovarian insufficiency and further cause female fertility." (PMID 36277066, 2022). "Recent studies found FANCA variants in patients with premature ovarian insufficiency (POI) and NOA." (PMID 35366911, 2022). "In a previous study about premature ovarian insufficiency (POI), two missense variants of FANCA were identified and could reduce its protein expression level compared with non-POI women." (PMID 33093844, 2020).
breast tumors (3 papers, 2014 to 2019). "Along the same line, a missense mutation in the FANCA protein identified in a breast tumor was shown responsible for increased FANCA SUMOylation." (PMID 31405039, 2019). "The only gene that was consistently upregulated in both retinoblastoma as well as in basal breast tumors was FANCA." (PMID 25161863, 2014). "Consistent with this, FANCA expression is up-regulated in basal breast tumors compared with non-basal breast tumors, and has higher expression levels in RB1-mutated retinoblastomas than MYCN-amplified retinoblastomas." (PMID 28239445, 2017).
Ewing sarcoma (3 papers, 2020 to 2025). A small round cell tumor that lacks morphologic, immunohistochemical, and electron microscopic evidence of neuroectodermal differentiation. "Germline pathogenic variants in DDR genes, including FANCC, CHEK2, and FANCA, have been reported as predisposing to the development of Ewing sarcoma." (PMID 40563612, 2025).
male infertility (3 papers, 2024 to 2025). The inability of the male to effect fertilization of an ovum after a specified period of unprotected intercourse. "Interestingly, one of these variants was previously associated with SPGF: rs372254398 (MAFALFA = 8.00E−05), which is located in the FA Complementation Group A (FANCA) locus (a gene with a ‘moderate’ amount of evidence of causing male infertility according to IMIGC)." (PMID 39678461, 2024). "A 2018 review identified 78 genes related to male infertility, but only two were convincingly linked to the SCOS phenotype, both of which are autosomal recessive, namely FANCA and FANCM." (PMID 41488147, 2025). "Next-generation sequencing has contributed to the identification of several unknown genetic alterations in the context of male infertility and azoospermia including FANCA, PLK4, WKN3, MEI1, ADAD2, and TEX11." (PMID 40747475, 2025).
metastatic prostate carcinoma (3 papers, 2020 to 2023). A carcinoma that arises from the prostate gland and has spread to other anatomic sites. "In metastatic prostate cancer, an expanded HRD panel included patients with mutations to BRCA1, BRCA2, ATM, FANCA, CHEK2, PALB2, NBN, or HDAC2." (PMID 35205643, 2022).
myelodysplastic syndrome (3 papers, 2022 to 2025). A clonal hematopoietic disorder characterized by dysplasia and ineffective hematopoiesis in one or more of the hematopoietic cell lines. "Overall, 16 patients (17.2%) had pathogenic variants, including FANCA, BRCA2, PMS2, ELANE, G6PC3 and VPS13B in patients with idiopathic neutropenia, and GATA2 in patients with suspected myelodysplastic syndrome." (PMID 40358701, 2025).
Sepsis (3 papers, 2021 to 2022). Sepsis is defined as life-threatening organ dysfunction caused by a dysregulated host response to infection. "The present report established the renal injury models by treating HK2 cells with LPS to explore the role of circ-FANCA and the underlying mechanism in sepsis-associated AKI in vitro." (PMID 33468219, 2021). "However, the function of circ-FANCA in the progression of sepsis-induced AKI and the underlying mechanisms involved remain unknown." (PMID 33468219, 2021). "In this study, we aimed to elucidate the role of circ-FANCA and the potential action mechanism in sepsis-induced AKI." (PMID 33468219, 2021). "Nonetheless, the potential target relationship between circ-FANCA and miR-93-5p in sepsis-stimulated AKI has been unexplored." (PMID 33468219, 2021). "Circ-FANCA (hsa_circ_0040994) is produced from precursor mRNA FANCA, and it is identified to be highly expressed in sepsis-stimulated AKI." (PMID 33468219, 2021). "Therefore, circ-FANCA functioned as a regulatory molecule in sepsis-engendered AKI via downregulating miR-93-5p and upregulating OXSR1." (PMID 33468219, 2021). "Mechanistically, the regulatory function of circ-FANCA/miR-93-5p/mRNA network was explored, which might provide a new perspective for the pathogenesis of sepsis-related AKI." (PMID 33468219, 2021). "As yet, it remains unclear how circ-FANCA contributes to the pathogenesis of sepsis-induced AKI." (PMID 36303545, 2022). "Additionally, circ-FANCA was documented to be highly expressed in sepsis-induced AKI." (PMID 33468219, 2021). "Therefore, we speculated that targeting circ-FANCA may be effective therapeutic method for sepsis-induced AKI remedy." (PMID 33468219, 2021).
amenorrhea (2 papers, 2019 to 2020). The absence of menses in a woman who has achieved reproductive age. "POI-11, who carried a heterozygous c.2340 T > G variant in FANCA, was married at 30 years of age and had secondary amenorrhea and POI when trying to conceive." (PMID 32962729, 2020).
cervical cancer (2 papers, 2021). A primary or metastatic malignant neoplasm involving the cervix. "Genes with known or likely deleterious variants among cervical cancer patients with DDR gene alterations were ATM (n = 3, 2.33%), BRCA2 (n = 3, 2.33%), ATR (n = 2, 1.55%), CHEK2 (n = 2, 1.55%), followed by BRCA1 (n = 1, 0.78%), FANCA (n = 1, 0.78%), MSH6 (n = 1, 0.78%), and RAD51D (n = 1, 0.78%)." (PMID 35071000, 2021).
chordoma (2 papers, 2024 to 2025). Chordomas are rare malignant tumors arising from embryonic remnants of the notochord in axial skeleton. "The most common mutations in pediatric chordoma cases were MRE11, FANCA, and MSH6, each individually appearing in two of the pediatric samples." (PMID 39941902, 2025).
head and neck cancer (2 papers, 2022 to 2025). A primary or metastatic malignant neoplasm affecting the head and neck. "In addition, we observed comparable depletion results upon knockdown of SNAP23 in a FANCA-null background versus WT background in Cal33 cells, another head neck cancer cell line." (PMID 41188232, 2025).
head and neck squamous cell carcinoma (2 papers, 2022 to 2025). A squamous cell carcinoma that arises from any of the following anatomic sites: lip and oral cavity, nasal cavity, paranasal sinuses, pharynx, larynx, and salivary glands. "Deletions and other SVs were reported to specifically accumulate in squamous cell carcinomas from FA (mostly FANCA-mutated) patients as opposed to sporadic head-and-neck squamous cell carcinomas." (PMID 39656916, 2025).
Hereditary breast cancer (2 papers, 2020 to 2023). Breast carcinoma that has developed in relatives of patients with history of breast carcinoma. "By this means, only FANCA mutations showed a statistically significant association with an increased cancer risk in the combined group of hereditary breast cancer (HBC) and HBOC (odds ratio (OR) = 3.14 (95% confidence interval (CI) 1.4–6.17) p = 0.003)." (PMID 32235514, 2020).
Infertility (2 papers, 2023 to 2024). "Studies have shown that patients with biallelic pathogenic variants of FANCA, FANCM, FANCD1, FANCU, and patients with monoallelic pathogenic variants of FANCA, FANCD1, FANCL exhibited gonadal dysfunction and infertility." (PMID 37563658, 2023).
lung squamous cell carcinoma (2 papers, 2018 to 2022). "In lung squamous cell carcinoma (LUSC), suppressed tumoral LAG-3 expression is linked to mutations in Cut Like Homeobox 1 (CUX1), FA Complementation Group A (FANCA), or NOTCH4 genes." (PMID 36077354, 2022). "CA4 and HMOX1 achieved the best AUC performance (AUC = 0.9 and AUC = 0.89) in liver hepatocellular carcinoma, LTC4S and NEUROD1 in lung adenocarcinoma (AUC = 0.998 and AUC = 0.994), FANCA and ARG2 in lung squamous cell carcinoma (AUC = 0.992 and AUC = 0.956)." (PMID 29304754, 2018).
microcephaly (2 papers, 2014 to 2024). A congenital or acquired developmental disorder in which the circumference of the head is smaller than normal for the person's age and sex. "They showed that FANCA- and FANCG- deficient embryos developed microcephaly due to apoptosis of proliferating neural stem and progenitor cells and the resulting decline in neuron production." (PMID 39224124, 2024).
sarcoma (2 papers, 2016 to 2023). A usually aggressive malignant neoplasm of the soft tissue or bone. "56.6% of all analyzed sarcoma samples carried alterations in HRR pathway genes; BRCA2, FANCA, and ATM were found among the top altered genes in 11, 10, and 8% of all cases, respectively." (PMID 36779660, 2023).
acute GVHD (1 paper, 2025). "In our study patients 8 and 9 are offsrpings of consanguineous Roma parents sharing the same aforementioned frameshift variant (FANCA: c.3445_3448dup) and they had a rather uncomplicated post-HSCHT course without acute GVHD." (PMID 40868424, 2025).
acute lymphoblastic leukemia (1 paper, 2025). Leukemia with an acute onset, characterized by the presence of lymphoblasts in the bone marrow and the peripheral blood. "Additionally, we stably knocked down FANCA in the acute lymphoblastic leukemia cell line RS4;11." (PMID 40111122, 2025).
acute monocytic leukemia (1 paper, 2025). Acute monoblastic leukemia (AML-M5), is one of the most common subtypes of acute myeloid leukemia (AML) that is either comprised of more than 80% of monoblasts (AML-M5a) or 30-80% monoblasts with (pro)monocytic differentiation (AML-M5b). "To further validate that loss of FANCA sensitizes AML cells to low concentration of volasertib, we stably knocked down FANCA using shRNA in four different AML cell lines: THP-1 (acute monocytic leukemia), HL60 (acute promyelocytic leukemia), Kasumi-1 (acute myeloblastic leukemia), and OCI-AML-5." (PMID 40111122, 2025).
angiosarcoma (1 paper, 2023). A malignant tumor arising from the endothelial cells of the blood vessels. "EME1, FANCA, RAD51, TP53BP1, RAD51C, RPA1, and XRCC2 exhibited alterations in more than half the cases of the angiosarcoma cohort." (PMID 36779660, 2023).
chronic lymphocytic leukemia (1 paper, 2022).
esophageal cancer (1 paper, 2024). A primary or metastatic malignant neoplasm involving the esophagus. "Earlier research conducted by Lachet al. revealed a correlation between elevated FANCA expression and the metastatic stage of esophageal cancer." (PMID 38682160, 2024).
esophageal squamous cell carcinoma (1 paper, 2015). Esophageal squamous cell carcinoma (ESCC) is a type of esophageal carcinoma (EC) that can affect any part of the esophagus, but is usually located in the upper or middle third. "Increased risk of esophageal squamous cell carcinoma (ESCC) was reported to be associated with mutations in FANCD2, FANCE, FANCL, and FANCA in patients from an Iranian population." (PMID 26596371, 2015).
female subfertility (1 paper, 2019). "In summary, our findings in human subjects and mice suggest that heterozygous pathogenic variants in FANCA could affect female fertility, providing novel insights into the molecular diagnosis of female subfertility and genetic counseling for women who are at a risk for POI." (PMID 31535215, 2019). "Collectively, our results suggest that heterozygous pathogenic variants in FANCA are implicated in non-syndromic POI in Han Chinese women, provide new insights into the molecular mechanisms of POI and highlight the contribution of FANCA variants in female subfertility." (PMID 31535215, 2019).
gastric adenocarcinoma (1 paper, 2020). "Here, we report a case in which a patient with a FANCA mutation developed thyroid papillary carcinoma and gastric adenocarcinoma." (PMID 32850347, 2020).
hereditary ovarian cancers (1 paper, 2021). "The gene test of this patient showed mutations of uncertain significance in FANCA, BRCA1, and BRIP1, which have been associated with hereditary ovarian cancers." (PMID 34941061, 2021).
Insulin resistance (1 paper, 2017). Increased resistance towards insulin, that is, diminished effectiveness of insulin in reducing blood glucose levels. "Patients with mutations in FANCA show a mild endocrine phenotype in which height is not severely affected and insulin resistance is mild, whereas mutations in FANCC, which are related to shorter stature, have the least insulin resistance." (PMID 29238724, 2017).
leiomyoma (1 paper, 2020). A well-circumscribed benign smooth muscle neoplasm characterized by the presence of spindle cells with cigar-shaped nuclei, interlacing fascicles, and a whorled pattern. "To find the possible association between the missense SNP rs2239359 in FANCA and the proliferation rate of leiomyoma, we performed direct sequencing." (PMID 33202820, 2020). "In this study, we found that FANCA missense SNP rs2239359 was associated with increased proliferation rate of leiomyoma in Korean women." (PMID 33202820, 2020). "Therefore, the loss of activity of FANCA could result in DNA damage and contribute to the differential growth rate of leiomyoma." (PMID 33202820, 2020). "Nevertheless, we found the relation between rs2239359 of FANCA and proliferation of leiomyoma in Korean women." (PMID 33202820, 2020). "Further studies establishing the mechanistic details to determine the effect of FANCA on thyroid function in relation to the growth of leiomyoma will be of great importance." (PMID 33202820, 2020). "The significance of this study lies in the finding of FANCA SNP rs2239359 as the possible determining factor for the differential growth rate of leiomyoma." (PMID 33202820, 2020). "Given the extent of genetic heterogeneity of the FANCA mutation and its involvement in diverse cellular functions, finding the association of FANCA missense SNP rs2239359 with the proliferation rate of leiomyoma in the current study was not surprising." (PMID 33202820, 2020).
meningioma (1 paper, 2025). A generally slow growing tumor attached to the dura mater. "Three pediatric cases were included: a spinal clear-cell meningioma (grade 2), an olfactory groove meningothelial meningioma (grade 1), and a sphenoid wing atypical meningioma (grade 2) with PTEN and FANCA pathogenic mutations." (PMID 40951339, 2025).
microphthalmia (1 paper, 2020). Congenital or developmental anomaly in which the eyeballs are abnormally small. "FANCA mutant mice exhibited growth retardation, microphthalmia, and craniofacial malformations." (PMID 33202820, 2020).
neurofibroma (1 paper, 2023). An intraneural or extraneural neoplasm arising from nerve tissues and neural sheaths. "Additional recurrent but low-frequency mutations in neurofibromas include FANCA, PTPRD, NF2, LZTR1, KNL1 and RUNX1." (PMID 37164978, 2023).
non-small cell lung carcinoma (1 paper, 2017). A group of at least three distinct histological types of lung cancer, including non-small cell squamous cell carcinoma, adenocarcinoma, and large cell carcinoma. "Another study showed that miR-503 regulates the resistance of non-small cell lung cancer cells to CDDP, at least in part, by targeting FANCA (Fanconi anemia complementation group A protein)." (PMID 29383199, 2017).
prostate tumor (1 paper, 2024). "We employed 14 patient-derived tumor graft models pancreatic, lung, and prostate tumor graft models harboring HR mutations (BRCA1/2, CHK1/2, ATM/ATR, PALB2, PARP1/2, RAD51, FANCA/B) to compare LP-184’s potency with PARPi olaparib." (PMID 38630886, 2024).
prostatic adenocarcinoma (1 paper, 2019).
squamous cell carcinoma of larynx (1 paper, 2017). "On the other hand, hypomethylation of FANCA promoters in squamous cell carcinoma of larynx (LSCC) cells has also been shown, which could mean that higher expression levels of these proteins contribute to oncogenic potential." (PMID 28239445, 2017).
thyroid cancer (1 paper, 2021). "By studying 6 PTMC patients and 6 cancer-free controls, we found that mutations in Rad50 and FANCA reduce DSB repair capacity and may lead to the occurrence of thyroid cancer." (PMID 34215272, 2021).